MYC (MYC proto-oncogene, bHLH transcription factor)
Diseases named in the same sentence as MYC in open-access papers (continued):
Sharing a sentence is not in itself a finding about the gene and the disease.
tumor (continued). "Therefore, TAF1 is a hub gene in both the normal and tumor lists, while HNF4A, MAX, and MYC are not." (PMID 35428183, 2022). "Our sequencing pipeline was able to detect the most prominent CNVs, such as the amplifications of MYC (22.2% of cases) and HER2 (22.2%), from the tumor DNA sequencing data, although the used gene panel was not specifically designed to identify CNVs from sequenced samples." (PMID 35267640, 2022). "Thus, our observations about the role of TWIST1 in enhancing NB tumor aggressiveness remain to be verified by both overexpression and KO experiments using NB cell lines without MNA with low or high MYC level, as well as with primary NB cells." (PMID 35022561, 2022). "In addition to MYC, EZH2 was previously shown to promote the expression of NF-κB targets and tumor cell growth independent of its histone methyltransferase activity in ER-negative basal-like breast cancer." (PMID 35013218, 2022). "Combined, these findings confirmed our previous results, where we saw that MYC expression directly hinders immune infiltration in BRCA1-mutant tumors and underscore that the decreased immunogenicity does not result from different tumor latencies or sizes." (PMID 36323660, 2022). "Moreover, they have been instrumental in defining specific mechanisms for tumor cell dormancy and cancer recurrence in the absence of oncogenic KRAS and c-MYC." (PMID 34491463, 2021). "This ternary complex, MYC/MIZ1/DNMT3A, methylates and actively suppresses p21CIP1 and p15INK4B promoter activity, leading to cell proliferation rather than differentiation and senescence during tumor progression." (PMID 33801599, 2021). "The tumor was negative for cytokeratins, p40, SOX2, and MYC and positive for NUT, FLI1, and CD99." (PMID 34898574, 2021). "Although MYC and TBX3 could partially mediate ZFHX3′s promoting effects on cell proliferation and tumor growth, direct evidence is still lacking at this time because findings from the rescue experiments were not conclusive." (PMID 33217982, 2020). "For instance, CRISPR‐mediated depletion of MYCL or MYCN in mouse tumor‐derived SCLC could reduce tumor formation capacity, but MYC could not." (PMID 32281704, 2020). "Hence, both Ccl2 and Il13 are sufficient to elicit MYC-HCC to metastasize, even if Twist1 is not expressed in the tumor cells." (PMID 31933479, 2020). "We did not detect any consistent changes in MYC and OTX2 expression upon modulation of the Activin pathway, suggesting that this signaling pathway does not regulate these two genes in Group 3 tumors and promotes tumor growth through other mechanisms." (PMID 31328883, 2019). "In addition, the focal high gain of the MYC locus (chr8) with at least 6 copies was identified in clones C and F and amplification of EGFR (chr7) was identified at over 35 copies in the bulk tumour samples but none of the derived clonal samples." (PMID 30736342, 2019). "Finally, the oncogene c-MYC regulates HIF1 expression regardless of oxygen levels, and both act in concert to “fine-tune” adaptive responses during tumor growth." (PMID 31921661, 2019). "Utilizing a MYC-driven model of T-ALL, Anderson and colleagues demonstrated that heterozygous inactivation of DLST (the E2 enzyme of KGDHC) was sufficient to significantly delay tumor onset without impacting normal animal development." (PMID 28748451, 2018). "On the other hand, even if no increase in tumor formation was found in mice carrying a single extra copy of PVT1 only, PVT1 may have oncogenic properties also independently of MYC." (PMID 28704924, 2017).
tumor (continued). "Overall, our data suggest that NBL tumor cells lacking MYCN amplification recruit and polarize macrophages to an M2-like phenotype, which in turn enhance NBL proliferation and growth through up-regulation of the MYC protein." (PMID 29207662, 2017). "However, it is also clear from our work, and others, that MYC levels are sufficiently high for transformation in the presence of HUWE1 and reduction or overexpression of MYC does not have a profound impact on tumour initiation." (PMID 28003334, 2017). "JQ1 treatment did not reduce either C-MYC or N-MYC expression, indicating that the anti-proliferative effect of JQ1 on tumor growth may not be directly related to modulating MYC expression." (PMID 27799065, 2016). "Although these functions of c-MYC have not been investigated in relation with miRNAs in MM, our recently published work shows that c-MYC regulates drug (PRIMA-1Met) response in MM cells by interacting with miR-29a (a tumor suppressor miRNA)." (PMID 27494872, 2016). "Intriguingly, MYC amplified tumor cells displayed a significantly higher production of total oxidized and reduced nicotinamide adenine dinucleotide phosphates (NADP+ and NADPH, respectively) when compared to non-amplified (MYC-) cells (P < 0.01)." (PMID 25970789, 2015). "The oncogenes MET, MYC, BCL2 (yellow and blue subgroups) were down-regulated in normal vs tumor." (PMID 23405235, 2013). "Overall, independent of MYC, the deacetylation mediated inhibition of several tumor suppressors including FoxO3, Rb, and Ku70, together suggest that SIRT1 has significant tumor promoting activity." (PMID 23024800, 2012). "Our results, however, show that MYC is not required for the isolated process of invasion, further suggesting that the HIS is a gene signature specific to the early metastatic steps of migration and invasion inside the primary tumor." (PMID 23113900, 2012). "To summarize, these findings indicate that targeting MYC to attenuate neutrophil infiltration within the TME can not only suppress tumor cell proliferation and invasion but may also contribute to inhibiting tumor immune escape." (PMID 40732268, 2025). "Interestingly, our results demonstrated that tunicamycin (TM), a well‐established ER stress inducer, failed to promote ERAD for both EZH2 and MYC, implying that substrate specificity for ERAD may be dependent on stress conditions as well as tumor type." (PMID 39823459, 2025). "In the MSK cohort, patients with FGFR2amp were enriched for MYC, RB1, and NMP1 alterations that were not noted on the G360 panel, which could be due to tumor heterogeneity or the low sample size of patients with FGFR2amp in the MSK cohort from a single institution." (PMID 38902956, 2024). "Heatmap analysis of gene expression in adherent cells and stem‐like tumor spheres revealed a negative correlation between YY2 and stem‐related factors, including CD44, SOX9, SALL2, KLF15, OCT4 (also known as POU class 5 homeobox 1 or POU5F1), MYC, ASCL1, and POU3F2." (PMID 37300334, 2023). "While MYC is ubiquitously and highly expressed in cells throughout development and in adult tissues, MYCL expression is predominantly restricted to both neonatal and adult lung tissue; in contrast MYCN expression is tumor specific and is not usually expressed in human adult tissues." (PMID 36765949, 2023). "In patient samples, high AR activity was similarly required for anti-tumor activity of BAT, as there was no patient with a low ARAMW score (defined by our cut-off of less than 0.6) who exhibited significant downregulation of MYC and/or clinical evidence of tumor regression by BAT." (PMID 36194476, 2022).
tumor (continued). "In addition, we also found that the MYC signaling activation group also showed higher intratumoral heterogeneity, IFN-gamma response and M1/M2 macrophages and lower TCR shannon, while the tumor purity and BCR shannon did not be significantly different between the two groups." (PMID 36299592, 2022). "In addition, MYC CNA was found in older individuals (p = 0.0007), which may be supportive of amplification at the MYC/PVT1 locus in tumor progression rather than initiation." (PMID 36139061, 2022). "However, in line with the lack of tumor formation in the brains of GL mice, we did not observe a significant increase in the abundance of selected Wnt and Shh targets (APC, GLI2, AXIN2, MYCN, MYC)." (PMID 34801069, 2021). "Grossly, numerous tumor nodules could be found in c-MYC/pCMV liver, but not in c-MYC/CRE livers." (PMID 32019910, 2020). "ATRi VE822 had the ability to penetrate the blood–brain/tumor barrier and, when combined with olaparib in vivo, abrogated PARPi-induced p-Chk1, increased apoptosis and DNA damage, and extended animal survival in orthotopic GBM models generated from either MYC-amplified or non-Myc GSCs." (PMID 31266951, 2019). "Interestingly, 2-HG may also have a tumor suppressive effect in non-mutant IDH leukemias by inhibiting m6A demethylase and destabilizing MYC transcripts." (PMID 30356832, 2018). "Accordingly each tumor was determined to have either MYCN protein overexpression [MYCN protein (+)] or MYCN protein negative/weak expression [MYCN protein (−)/(+/−)] and either MYC protein overexpression [MYC protein (+)] or MYC protein negative/weak expression [MYC protein (−)/(+/−)]." (PMID 29464082, 2018). "Therefore, by addressing similar but not identical issues in different tumor models, all together these data strongly support the idea that targeting the MRN complex might represent a good strategy to tackle MYC(N)-driven tumors." (PMID 30166519, 2018). "However, it is to be noted that in both cell lines and tumours, data showed a trend that was not statistically significant given the low number of samples analysed and the huge heterogeneity of expression shown by HMGA1, FOS and MYC in tumors." (PMID 22363436, 2012). "In addition, our in vivo experiments showed no significant reduction in tumor outgrowth in response to SUMOylation inhibition as single compound therapy, whereas literature suggest that SUMO abolishment by genetic knock down of the E1 enzyme does reduce tumor outgrowth in MYC dependent tumors." (PMID 36792656, 2023). "While this second explanation is unlikely, as NKG2D expression is notably low in tumour-infiltrating NK cells, no study thus far has attempted to specify whether NKG2D expression differs between molecular subgroups, or particularly aggressive forms of MBL, such as the MYC-amplified subset." (PMID 37232837, 2023). "Enhanced oncogenic activity of both c-MYC and PCAT-1 in PC may be additionally attributed to the rs72725854-habouring enhancer present in a non-coding region of the 8q24 locus which gains enhancer activity in PC cell lines and tumours, but not in normal prostate tissues." (PMID 35159022, 2022). "This can explain the antitumorigenic effects of HIF-1α in cancers with low MYC oncogenic dependency and demonstrates the complexity of HIF-α in highly MYC oncogenic cancers, suggesting that solely inhibiting HIF-1α may result in preliminary attenuation, but have no impact on overall tumor burden." (PMID 35267567, 2022).
cancer (6,730 papers, 1995 to 2026). A tumor composed of atypical neoplastic, often pleomorphic cells that invade other tissues. "Despite playing critical roles in general transcription, inhibition of CDK7 and BRD4 have been implicated in preferential downregulation of cancer-related genes, such as MYC, thereby selectively killing cancer cells." (PMID 41505030, 2026). "Dysregulation of MYC has been implicated in various diseases, including cancer and neurological disorders." (PMID 39129166, 2025). "The overexpression of MYC is a hallmark of many cancer types and has been shown to directly initiate malignant transformation in various malignancies." (PMID 40428124, 2025). "MYC is a highly warranted therapeutic target due to its broad role in cancer development, its overexpression in variety of cancers (> 50% of all cancers), and its association with therapy resistance and poor prognosis." (PMID 39779613, 2025). "For example, the E3 ligase FBW7 is frequently mutated in human cancer due to its ability to target oncoproteins such as MYC for proteasomal degradation." (PMID 40473213, 2025). "This innovative strategy was developed as a novel approach for the specific inhibition of these miRNAs’ function with a focus on blocking MYC dosage compensation as MYC amplifications are a hallmark feature of many cancers." (PMID 40940795, 2025). "GSEA revealed that the high-risk group was significantly enriched in multiple cancer-related Hallmark pathways, including Mtorc1 signaling, MYC targets V1/V2, Unfolded protein response, and Wnt beta catenin signaling (FDR <0.05)." (PMID 39925852, 2025). "Gene set enrichment analysis (GSEA) demonstrated a positive correlation between high PRDX1 expression and pathways associated with the cell cycle, cancer, and drug resistance, including DNA synthesis, MYC targets, and ATP-binding cassette(ABC) transporters." (PMID 40825764, 2025). "Lastly, isoTWAS identifies 52 genes (34 undetected by TWAS) that are associated with five or more cancer outcomes, including multiple known oncogenes or tumor suppressor genes, such as MYC, MUTYH, GNAI2, ACO2, and BMI1." (PMID 40775447, 2025). "The expression levels of cancer stem cell-associated genes STAT3, SOX2, and MYC, varied among cancer cell clusters." (PMID 40883281, 2025). "Intriguingly, the majority of cancer-associated mutations within c-MYC predominantly target these residues or their adjacent counterparts." (PMID 40034124, 2025). "This suggests that elevated levels of miR-664b-3p can suppress Rheb expression, thereby inhibiting downstream mTORC1 activity and reducing c-MYC-mediated metabolic reprogramming, a hallmark of cancer progression." (PMID 41004517, 2025). "A region located upstream of the MYC oncogene that carries more risk for inherited cancer than any other human genomic region is required for intestinal regeneration." (PMID 40180576, 2025). "Aurora kinases are a family of serine/threonine kinases involved in cell division and implicated in MYC-amplified cancers." (PMID 39779613, 2025). "This indicates that MYC activation can bypass the pharmacological inhibition of YAP/TAZ-TEAD signaling in cancers where Hippo pathway is mutationally inactivated." (PMID 41347094, 2025). "The UPS is expected to play a role in cancer immune evasion by controlling the stability and activity of the PD-1, PD-L1, or MYC proteins, depending on the context and driver mutations." (PMID 39851497, 2025). "Recent studies suggest the MYC as a master regulator in host immune response against the cancer but mainly focusing on the mutational activation of MYC." (PMID 40894230, 2025). "Our analysis reveals a cross-regulatory network among splicing factors, involving protein–protein and splicing-mediated interactions, with MYC and additional candidate pathways linking cancer driver mutations to splicing regulation." (PMID 41101775, 2025).
cancer (continued). "MYC directly regulates nuclear-encoded mitochondrial genes and drives mitochondrial biogenesis, enabling cancer cells to maintain a high OXPHOS capacity despite elevated levels of glycolysis." (PMID 40668928, 2025). "GSEA based on the cancer hallmark gene sets revealed significant inhibition of MYC targets, E2F targets, G2M checkpoint, and mTORC1 signaling pathways in AZ628-treated IOMM-Lee cells." (PMID 41184266, 2025). "c-MYC is a transcription factor involved in cancer cell proliferation, and its expression has been associated with chemoresistance." (PMID 41438985, 2025). "One of the core findings of this analysis is the differential response of Hallmark cancer pathways, including MYC, E2F targets, and the G2/M checkpoint, to chemotherapy treatments." (PMID 41392193, 2025). "Among the key oncogenes implicated in cancer is c-MYC, which encodes a transcription factor involved in regulating crucial cellular processes such as cell-cycle progression, differentiation, apoptosis, DNA replication, and mRNA maturation." (PMID 41226615, 2025). "c-MYC is a pivotal oncogene, whose aberrant activation is strongly linked to enhanced cancer cell proliferation, metabolic reprogramming, and the promotion of tumorigenesis." (PMID 40333779, 2025). "The TAF10 protein has been linked to the transcriptional activation of MYC resulting in over-expression in cancer cells." (PMID 40227817, 2025). "Gene set enrichment analysis (GSEA) further revealed that genes in VPS25high cancer cells were enriched in pathways associated with cell proliferation, including DNA repair mechanisms, MYC targets, and E2F targets." (PMID 40149859, 2025). "MYC’s additional (or potentially entirely linked) roles as a driver of pluripotency and cancer also match observations here of a highly skewed baseline transcriptional profile in transformed and undifferentiated cell types such as ES cells." (PMID 40341320, 2025). "Expanding on our observation of cancer-type-specific regulation of MYC, we identified 51 oncogenes with >5 linked differential H3K27ac peaks, nominating tissue-specific regulatory elements." (PMID 40355593, 2025). "c-MYC is a group of proto-oncogenes and regulator genes that encode transcription factors, whereas Bcl-2 is overexpressed in cancer cells and inhibits pro-apoptotic signals to enable cancer cells to survive in adverse conditions." (PMID 39852063, 2025). "Cancer-associated genetic alterations in MYC, PIK3CA, PTEN, KRAS, and BRAF dysregulate growth-promoting signals, enhancing ribosome production and protein synthesis." (PMID 40805230, 2025). "While MYC alterations are observed in a broad array of cancers, MYCN is especially implicated as a key factor in paediatric cancers originating from central and peripheral nervous system tissues." (PMID 40779030, 2025). "Research has demonstrated that MYC inhibitors can enhance immunogenic pathways and make cancer cells more susceptible to immune attack." (PMID 40552293, 2025). "The observed increase in MYC activity and ribosome biogenesis aligns with previous studies showing that MYC is a key regulator of ribosome biogenesis, and both processes are implicated in drug resistance in yeast and human cancers." (PMID 41019980, 2025). "Mutations or amplifications that lead to the overexpression of the MYC gene cause normal cells to transform into aggressive, highly proliferative cancer cells." (PMID 41155227, 2025). "Since MYC dysregulation is observed in approximately 70% of all cancers and plays a causal role in cancer progression, it is a promising target for anticancer therapy." (PMID 41025936, 2025). "The colon cancer associated transcript 1 (CCAT1) is a lncRNA gene that exists in the sparsely protein coding and highly cancer associated locus of 8q24.21, where both MYC and PVT1 also reside." (PMID 40521240, 2025).